RARRES1 (retinoic acid receptor responder 1)
Diseases named in the same sentence as RARRES1 in open-access papers (continued):
Sharing a sentence is not in itself a finding about the gene and the disease.
choriocarcinoma (3 papers, 2017 to 2024). An aggressive malignant tumor arising from trophoblastic cells. "Here, we detected a high RARRES1 expression in VTs and EVTs and a loss of RARRES1 in malignant choriocarcinoma cells." (PMID 29169400, 2017). "This process is important for the induction of cancer cell EMT and might explain the loss of RARRES1 expression in choriocarcinoma cases." (PMID 29169400, 2017). "Our data demonstrated that RARRES1 expression is lost in choriocarcinoma cases due to promotor hypermethylation." (PMID 29169400, 2017). "RARRES1 protein expression analysis by immunohistochemistry allowed the discrimination of intramolar and pure choriocarcinoma cases." (PMID 29169400, 2017). "Additionally, RARRES1 was stained in healthy placentas and in biopsies of choriocarcinoma cases (n = 10) as well as the first trimester trophoblast cell line Swan71 by immunofluorescence and immunohistochemistry." (PMID 29169400, 2017). "In line with its proposed tumor suppressor function, RARRES1, along with RARRES2, was reduced in choriocarcinoma and its expression was also significantly reduced in certain choriocarcinoma cell lines (i.e., Jeg-3 and BeWo)." (PMID 31905805, 2019). "Our findings showed that RARRES1 expression is absent in choriocarcinoma due to promoter methylation." (PMID 29169400, 2017). "Regardless of secondary side-effects, we hypothesize that RARRES1 expression and functional activity might be lost in choriocarcinomas, supporting the concept that placental RARRES1 might act in a suppressive manner and in cases of choriocarcinoma as a tumor suppressor." (PMID 29169400, 2017).
diabetic kidney disease (3 papers, 2024 to 2025). Progressive kidney disorder caused by vascular damage to the glomerular capillaries, in patients with diabetes mellitus. "Additionally, RARRES1 expression in glomeruli, predominantly in podocytes, is elevated in patients with diabetic kidney disease." (PMID 41369384, 2025). "Molecular profiling of patients with diabetic kidney disease (DKD) has indicated that RARRES1 is produced in glomerular endothelial cells (GECs) but is not detected in diabetic patients without DKD." (PMID 38374141, 2024).
hepatocellular carcinoma (3 papers, 2016 to 2024). A malignant tumor that arises from hepatocytes. "Although RARRES1 is among the most commonly methylated genes in multiple cancers, it is increased in basal-like hormone receptor negative breast cancer and in liver cirrhosis, a risk factor for hepatocellular cancer." (PMID 34717732, 2021).
Obesity (3 papers, 2018 to 2025). Accumulation of substantial excess body fat. "Using various obesity-related DN mouse models, we showed that ST32da-induced ATF3 benefits obesity-related DN and improves high-glucose-induced inflammatory reactions in mesangial cells by inhibiting the proapoptotic molecule RARRES1, activated via the paracrine pathway." (PMID 41369384, 2025). "Among the genes affiliated with the 119 significant CpGs, SOCS3 and DOK2 were differentially expressed in the SAT of obesity patients, while seven genes (SOCS3, PRR5L, ABCG1, BRDT, B3GNT7, ZNF710, and RARRES1) were differentially expressed in the VAT of obesity patients." (PMID 30619480, 2018). "Retinoic acid receptor responder 1 (RARRES1) is silenced in many cancers and is differentially expressed in metabolism associated diseases, such as hepatic steatosis, hyperinsulinemia and obesity." (PMID 30557378, 2018).
ovarian carcinoma (3 papers, 2019 to 2024). A malignant neoplasm originating from the surface ovarian epithelium. "The impaired mRNA levels of RARβ and RARRES1 in ovarian cancer tissues were further confirmed in the Oncomine database, suggesting that expression of retinoid-related genes is altered in human ovarian cancer cells." (PMID 31615043, 2019). "Furthermore, we found that RARRES1, retinoic acid receptor responder 1, was strongly downregulated (approximately 14-fold) in ovarian cancer cells lines." (PMID 31615043, 2019). "Compared with the other five OMAGs, the overall expression level of RARRES1 in ovarian cancer cell lines was not high." (PMID 36424614, 2022).
renal carcinoma (3 papers, 2022 to 2024). A carcinoma arising from the epithelium of the renal parenchyma or the renal pelvis. "The CCK-8 assay results showed that M1 macrophages significantly decreased the viability of renal carcinoma cells after being cocultured with RARRES1-overexpressing RCC cells." (PMID 36353618, 2022). "We showed that M1 macrophages more significantly decreased the viability of RARRES1-overexpressing renal carcinoma cells and increased the apoptosis rate of renal carcinoma cells." (PMID 36353618, 2022). "In addition, RARRES1 overexpression in renal carcinoma cells enhanced the migration potential of M1 macrophages." (PMID 36353618, 2022). "A recent study revealed that RARRES1 exerts an anti-tumor effect by promoting ICAM1 expression and inducing M1 macrophage activation in renal cancer in vitro." (PMID 38533207, 2024).
triple-negative breast carcinoma (3 papers, 2018 to 2024). An invasive breast carcinoma which is negative for expression of estrogen receptor (ER), progesterone receptor (PR), and human epidermal growth factor receptor 2 (HER2). "However, RARRES1 is increased in some mesenchymal-like cancers such as triple negative breast cancer." (PMID 30557378, 2018).
atherosclerosis (2 papers, 2010 to 2021). A disease characterized by the build-up of fatty material and calcium deposition in the arterial wall resulting in partial or complete occlusion of the arterial lumen. "For example, it has been reported that retinoic acid (RA) reduces plaque formation in an atherosclerosis prone mouse model, and here, we observed an upregulation of RA receptors (RARB) and two RA receptor responsive genes (DHRS3 and RARRES1) following abrogation of AMPA receptor signaling." (PMID 33959644, 2021).
atopic dermatitis (2 papers, 2024 to 2025). "RARRES1 has been implicated in inflammatory conditions such as pterygium, psoriasis, and atopic dermatitis." (PMID 41178994, 2025).
clear cell renal cell carcinoma (2 papers, 2024 to 2025). "For example, in renal clear cell carcinoma, RARRES1 plays an anti-tumor role by promoting ICAM1 expression and inducing the activation of M1 macrophages." (PMID 40002669, 2025).
COVID-19 (2 papers, 2023). A disease caused by infection with severe acute respiratory syndrome coronavirus 2. "Among these, four (CLEC4A, DSG4, FAM3B, and RARRES1) displayed significantly lower levels in both moderate and severe COVID-19, as compared to the healthy controls and the sepsis cohorts." (PMID 36829233, 2023). "We successfully identified the shared 6 candidate gene signatures (RRM2, EGF, TMEM252, RARRES1, COL6A3, CUBN) between COVID-19 and AKI." (PMID 37789254, 2023). "The results revealed that 6 key gene signatures (RRM2, EGF, TMEM252, RARRES1, COL6A3, CUBN) were recognized to have great influences on COVID-19 and AKI." (PMID 37789254, 2023).
leukemia (2 papers, 2018 to 2020). A malignant (clonal) hematologic disorder, involving hematopoietic stem cells and characterized by the presence of primitive or atypical myeloid or lymphoid cells in the bone marrow and the blood. "The other significant findings were RARRES1 was down regulated in old patients, implicated in retinoid therapy and found to be as a tumor suppressor for multiple cancers such as prostate, breast, gastric, leukemia." (PMID 33575208, 2020).
osteosarcoma (2 papers, 2024). A usually aggressive malignant bone-forming mesenchymal neoplasm, predominantly affecting adolescents and young adults. "In the literature, RARRES1 has been identified as a tumor suppressor gene in several malignancies, including renal cell carcinoma, follicular lymphomagenesis, and osteosarcoma." (PMID 38773060, 2024).
pterygium (2 papers, 2021 to 2025). A wedge-shaped fibrovascular lesion arising from the bulbar conjunctiva and extending to the cornea. "Among the top DEGs were four genes encoding tumor suppressors that were downregulated in pterygium: C10orf90, RARRES1, DMBT1 and SCGB3A1; C10orf90 and RARRES1 were also downregulated in pinguecula." (PMID 34769520, 2021). "An early microarray study also reported downregulation of RARRES1 in pterygium." (PMID 34769520, 2021). "In addition, the previous RNA-seq study reported RARRES1 as one of the top downregulated DEGs in pterygium." (PMID 34769520, 2021). "RARRES1 and SCGB3A1 were identified in previous pterygium gene profiling studies, while C10orf90 and DMBT1 are new." (PMID 34769520, 2021).
testicular cancer (2 papers, 2024). A primary or metastatic malignant neoplasm that affects the testis. "Studies have shown a significant downregulation of RARRES1 expression in several types of cancers, including prostate, colorectal, nasopharyngeal, gastric, endometrial, and testicular cancers." (PMID 38898266, 2024). "On downregulation of SPINK2 in testicular cancer tissues, the combined effect of SPINK2 and RARRES1 significantly inhibits testicular cancer cell EMT by downregulating the uPA/uPA receptor signaling pathway." (PMID 38388961, 2024).
thyroid cancer (2 papers, 2017 to 2022). "Interestingly, there is relative lack of knowledge on the role of the remaining three genes, i.e. IMMP2L, RARRES1 and CARD9-SNAPC4 in thyroid cancer." (PMID 35976137, 2022).
Cholestatic liver disease (1 paper, 2018). "RARRES1 is also differentially expressed in mouse models of hepatic steatosis and cholestatic liver disease." (PMID 30557378, 2018). "RARRES1 increased during dedifferentiation of adipocytes and decreased during differentiation and is differentially expressed in mouse models of hepatic steatosis and cholestatic liver disease." (PMID 30557378, 2018).
choroidal neovascularization (1 paper, 2025). An eye disorder described by the growth of new blood vessels that originate from the choroid through a break in the Bruch membrane into the sub–retinal pigment epithelium (sub-RPE) or subretinal space. "RARRES1 expression was examined in aqueous humor, laser-induced choroidal neovascularization (CNV) model mice, and human ARPE-19 cells exposed to H2O2." (PMID 41178994, 2025).
collecting duct carcinoma (1 paper, 2020). "RARRES1 RNA was also highly expressed in the two collecting duct carcinoma, as well as in four papillary RCC with metastatic growth, but no expression was seen in renal oncocytomas and chromophobe RCCs." (PMID 32307444, 2020).
colon cancer (1 paper, 2016). "This supports previous findings in which RARRES1 expression was associated with SUMO2 expression in HCT116 colon cancer cells." (PMID 27286452, 2016).
dry eye (1 paper, 2019). "Of these proteins, CEACAM7 and RARRES1 have not yet been connected to ocular surface condition and while ACTG1 is an interesting protein, it has so far been only connected to treatment effects of dry eye." (PMID 30976209, 2019).
endometriosis (1 paper, 2024). The growth of functional endometrial tissue in anatomic sites outside the uterine body. "For example, the retinoic acid receptor responder 1 (RARRES1) was significantly decreased in endometriosis across all the time points." (PMID 38402336, 2024).
follicular lymphoma (1 paper, 2022). Follicular lymphoma is a form of non-Hodgkin lymphoma characterized by a proliferation of B cells whose nodular structure of follicular architecture is preserved. "In two mouse strains, loss of Rarres1 led to a markedly increased dose-dependent incidence of follicular lymphoma (FL)." (PMID 35541897, 2022). "We discovered that Rarres1 deletion in two independently derived strains of mice leads to the development of indolent follicular lymphoma (FL) starting around one year of age." (PMID 35541897, 2022). "Our work suggests that the well-known age-dependent epigenetic silencing of RARRES1 expression can enhance follicular lymphoma development." (PMID 35541897, 2022). "Here, we have discovered that genetic knockout of Rarres1 in mice leads to almost complete penetrance of follicular lymphoma." (PMID 35541897, 2022). "However, the life-time incidence of follicular lymphoma was dramatically higher in Rarres1-/- mice (70/90, 77.8%) compared to heterozygotes (Rarres1+/-, 40/90, 44.4%) and WT mice (2/100, 2%)." (PMID 35541897, 2022).
food allergy (1 paper, 2022). Gastrointestinal disturbances, skin eruptions, or shock due to allergic reactions to allergens in food. "Within these, 113 genes (27.8%) have been previously associated with food allergy; within the top 10 DE genes, 8 genes have been previously linked to food allergy—C3, CXCL8, RARRES1, CXCL6, MUC5AC, CXCL1, and SAA3." (PMID 36452260, 2022).
Hyperinsulinemia (1 paper, 2018). An increased concentration of insulin in the blood. "Examination of deposited microarray data from a study focusing on hyperinsulinemia indicated that RARRES1 was also markedly decreased after insulin treatment in human skeletal muscles." (PMID 30557378, 2018).
joint disease (1 paper, 2022). "There are no data on the effect of RARRES1 on the development of joint disease, but it has been shown to have pro-inflammatory and fibrosis-promoting effects through activation of the NF-κB signaling pathway." (PMID 36233118, 2022).
liver cancer (1 paper, 2024). An epithelial or non-epithelial malignant neoplasm that arises from the liver. "We used siRNAs to knockdown RARRES1 and determine the role of RARRES1 in liver cancer cell proliferation and apoptosis, and the results showed that silencing RARRES1 increased cell viability and cell colony numbers, as well as decreasing the rate of apoptosis and HCC cell sensitivity to lenvatinib." (PMID 38388961, 2024).
lymphoma (1 paper, 2022). A malignant (clonal) proliferation of B- lymphocytes or T- lymphocytes which involves the lymph nodes, bone marrow and/or extranodal sites. "As knockout of Lxn in mice increases the numbers of HSPCs and mature blood cells, we wanted to know if RARRES1 loss could increase the numbers of B cells before FL development thereby increasing the risk for lymphoma development." (PMID 35541897, 2022). "Prior to lymphoma formation, Rarres1-/- B cells have compromised activation, maturation, differentiation into antibody-secreting plasma cells, and cell cycle progression." (PMID 35541897, 2022). "Lymphoma onset in the Rarres1-/- mice is first detectable around 1 year of age." (PMID 35541897, 2022). "However, prior to the development of lymphoma, Rarres1-/- B cells had compromised activation, cell cycle progression, and differentiation into antibody-secreting plasma cells." (PMID 35541897, 2022). "In this study, we show that constitutive Rarres1 ablation leads to a high incidence of indolent FL, with a disease course that is remarkably similar to the human disease, including the presence of DLBC-like lymphomas at multiple sites in many animals." (PMID 35541897, 2022). "Although we did investigate the function of WT and Rarres1-/- B cell preparations isolated prior to lymphoma development, these were short term experiments and do not formally rule out a role for a prior influence of the Rarres1-/- niche cells." (PMID 35541897, 2022). "Since there was no change in the level of B cell numbers in the blood and spleen of Rarres1-/- mice prior to lymphoma formation, it is not simply the higher production of B cells that accounts for FL development." (PMID 35541897, 2022).
metastatic prostate carcinoma (1 paper, 2018). A carcinoma that arises from the prostate gland and has spread to other anatomic sites. "For example, hormone-negative breast cancers (e.g. TNBC vs. non-TNBC, ER+ vs. ER-, PR+ vs. PR-) and metastatic prostate cancer have differential RARRES1 gene expression." (PMID 30557378, 2018).
neurofibroma (1 paper, 2014). An intraneural or extraneural neoplasm arising from nerve tissues and neural sheaths. "LC-MS/MS analysis of conditioned media from primary neurofibroma Schwann cells compared to Schwann cells from normal nerve tissue identified a secreted form of retinoic acid responder 1 (RARRES1) from neurofibroma Schwann cells." (PMID 24713112, 2014).
oral cancer (1 paper, 2021). "Another gene targeting tretinoin, the retinoic acid receptor responder 1 (RARRES 1) gene, was found to play tumor suppressive function by negatively regulating metastasis; however, its immunological function in oral cancer has not yet been researched." (PMID 34422810, 2021).